ALK (ALK receptor tyrosine kinase)
Diseases named in the same sentence as ALK in open-access papers (continued):
Sharing a sentence is not in itself a finding about the gene and the disease.
anaplastic large cell lymphoma (continued). "Conversely, HDAC1 acts as a tumor suppressor in ALK-positive anaplastic large cell lymphoma." (PMID 41444923, 2025). "A diagnosis of ALK-positive anaplastic large cell lymphoma (ALCL) was rendered." (PMID 41366174, 2025). "Moreover, crizotinib was also approved for relapsed/refractory ALK-positive anaplastic large cell lymphoma (ALCL)." (PMID 39001541, 2024). "In fact, ALK rearrangements are a hallmark of anaplastic large cell lymphoma (ALCL) and have also been identified in a subset of non-small cell lung cancer (NSCLC)." (PMID 39767726, 2024). "Anaplastic lymphoma kinase (ALK) is found in a subtype of anaplastic large cell lymphoma." (PMID 38403820, 2024). "It concluded that ALK inhibitors should be accessible to children with anaplastic large cell lymphoma and inflammatory myofibroblastic tumor and that there was a deficiency of clinical trials and regulatory submissions: their submission was strongly encouraged." (PMID 37975877, 2024). "The differential diagnosis initially included classic Hodgkin lymphoma, nodular lymphocyte predominant Hodgkin lymphoma, EBV positive DLBCL, T cell/histiocyte rich large B cell lymphoma, anaplastic lymphoma kinase (ALK) positive large B lymphoma, and anaplastic large cell lymphoma." (PMID 39055348, 2024). "Anaplastic lymphoma kinase (ALK) is a receptor tyrosine kinase, initially discovered in anaplastic large cell lymphoma, but chromosomal rearrangements resulting in a fusion gene, most commonly with echinoderm microtubule-associated protein-like 4 (EML4), occur in 3-7% of NSCLC." (PMID 36910642, 2023). "Besides NSCLC, inflammatory myofibroblastic tumor (~50% have ALK fusions/rearrangements) and anaplastic large cell lymphoma (~50–80% having ALK fusions/rearrangements) are the neoplasms most frequently bearing ALK fusions." (PMID 37773318, 2023). "Our study raised the possibility that alectinib‐included therapeutic regimens might benefit the early response, in‐depth molecular remission, and persistent remission in children with ALK‐positive Anaplastic large cell lymphoma." (PMID 36408869, 2023). "Pathologists also use immunostains to provide information on the prognosis (for example, “triple-negative” breast cancer usually follows an aggressive course, whereas ALK-positivity portends a favorable prognosis in anaplastic large cell lymphoma), or guide clinical treatment decisions." (PMID 37240443, 2023). "Although DNA methylation profiling has shown a possible thymic origin for both ALK-positive and ALK-negative anaplastic large cell lymphoma (ALCL), suggesting a common cellular origin, driver genetic alterations have recently emerged in ALK-negative ALCL that are distinct from ALK-positive ALCL." (PMID 35330161, 2022). "ALK-positive anaplastic large cell lymphomas (ALCLs) represent a distinct subset of lymphomas that are associated with better outcomes in comparison to ALK-negative ALCLs." (PMID 35233056, 2022). "Anaplastic large cell lymphoma positive for ALK (ALK+ ALCL) is a rare type of non-Hodgkin lymphoma." (PMID 35246138, 2022). "However, case reports have discussed responses with crizotinib in ALK-positive anaplastic large cell lymphoma (ALCL) as well as ALK-translocated inflammatory myofibroblastic tumor (IMT)." (PMID 33738448, 2021). "Among PTCL, the 5‐year OS was highest in ALK+anaplastic large cell lymphoma (79.0%), followed by ALK−anaplastic large cell lymphoma (63.1%), natural killer/T‐cell lymphoma (57.7%), angioimmunoblastic T‐cell lymphoma (34.9%, and peripheral T‐cell lymphoma not otherwise specified (27.6%)." (PMID 32281275, 2020). "Notably, increased levels of Id2 are also present in anaplastic large cell lymphomas that result from constitutive activation of the Midkine receptor, ALK." (PMID 31882403, 2020). "This scenario is similar with anaplastic large cell lymphoma, whose PD-L1 status is associated with ALK positivity but not its outcome." (PMID 33273548, 2020).
anaplastic large cell lymphoma (continued). "However, after testing on a large panel of 120 kinases, it was found that crizotinib also potently inhibits ALK and induces apoptosis in anaplastic large-cell lymphoma." (PMID 31278140, 2019). "Finally, overexpression of PIM1 is similarly found to induce resistance to brigatinib and ceritinib in cell lines derived from ALK-positive anaplastic large cell lymphoma (ALCL)." (PMID 31780656, 2019). "Anaplastic lymphoma kinase (ALK)-negative anaplastic large cell lymphoma (ALCL) is a highly malignant non-Hodgkin lymphoma of CD30-positive T-cells that lacks chromosomal rearrangements of the ALK gene encoding a receptor tyrosine kinase." (PMID 29758012, 2018). "Among 17 NHL cases, 12 cases were confirmed mucosa associated lymphoid tissue B lymphoma type, 3 cases were confirmed diffuse large B- cell lymphoma, one case were confirmed angioimmunoblastic T-cell lymphoma and ALK positive anaplastic large cell lymphoma separately." (PMID 29530011, 2018). "In lung adenocarcinoma and anaplastic large-cell lymphoma, ALK is activated by the expression of chimeric proteins containing the ALK kinase domain, whereas ALK activation in neuroblastoma (NB) and rhabdomyosarcoma (RMS) results in the overexpression of wildtype or mutated transcripts." (PMID 29755689, 2018). "Anaplastic lymphoma kinase (ALK) is a tyrosine kinase receptor that was first described in 1994 with the characterization of a frequently occurring translocation within a subset of patients with anaplastic large-cell lymphoma (ALCL)." (PMID 28895885, 2017). "In the ER+ breast cancer and ALK-positive anaplastic large cell lymphoma models, Sox2 was found to be the key determinant of the SRR2 reporter activity (i.e. the RR phenotype), since siRNA knockdown of Sox2 in these cells resulted in a significant loss of cancer stemness features." (PMID 28427212, 2017). "Genetic aberrations in the ALK gene were first described in anaplastic large cell lymphoma by Morris and colleagues as part of an oncogenic fusion protein resulting from the translocation between chromosomes 2 and 5 (t [p23;q35]) (NPM-ALK - Nucleophosmin- anaplastic lymphoma kinase)." (PMID 28549458, 2017). "Sections of healthy colon tissue (Maixin Bio, Fuzhou, China) served as the positive controls for the expression of vimentin, SMA, desmin, AE1/AE3, S-100, DOG1, CD34 and CD117, and an ALK-positive anaplastic large cell lymphoma cell line (Maixin Bio) served as the positive control for ALK staining." (PMID 25663910, 2015). "The possibility that some of these lesions are neoplastic was discussed almost 50 years ago by Umiker and Iverson; other recent studies on a limited number of cases have demonstrated the presence of clonal cytogenetic abnormalities and ALK expression similar to the anaplastic large cell lymphoma." (PMID 25688324, 2015). "Bim was shown to be epigenetically silenced in NPM/ALK+ anaplastic large cell lymphoma (ALCL)." (PMID 26405162, 2015). "However in the ALK + ve large cell lymphoma the cells have a t [p23;q35] reciprocal translocation that activates the anaplastic lymphoma kinase gene that leads to abnormal proliferation and resistance to apoptosis." (PMID 25605631, 2015). "In addition to anaplastic large-cell lymphoma, ALK fusion genes have also been described in half of the inflammatory myofibroblastic tumors and rare ALK-positive diffuse large B-cell lymphomas." (PMID 25527865, 2014). "In addition to its physiologic expression, ALK is aberrantly expressed in several human cancers, including an aggressive subtype of T-cell lymphoma known as ALK-expressing anaplastic large-cell lymphoma (ALK+ ALCL)." (PMID 25026277, 2014). "Cucurbitacin I appears to be a potent inhibitor in meningioma cells and effective at concentrations similar to that effective on nasopharyngeal carcinoma cells and lower than effective on ALK-positive anaplastic large cell lymphoma cells and pancreatic carcinoma cells." (PMID 24188277, 2013).
anaplastic large cell lymphoma (continued). "Indeed, several cases in the literature were initially classified as poorly differentiated or anaplastic carcinoma, ALK-positive anaplastic large cell lymphoma (ALK+ ALCL), or extramedullary plasmacytoma." (PMID 22474449, 2012). "All T-cell lymphomas behave aggressively except ALK-positive anaplastic large cell lymphoma." (PMID 21188274, 2010). "The prognosis of PTCL is poor with the exception of the ALK (anaplastic lymphoma kinase) expressing anaplastic large cell lymphoma (ALCL) with a more favourable outcome after conventional chemotherapy and the primary cutaneous T-cell lymphomas (CTCL) that usually show an indolent clinical course." (PMID 21253465, 2010). "A diagnosis of primary systemic anaplastic large-cell lymphoma, ALK+, T-cell-type was made." (PMID 20977317, 2010). "Teleologically, this anomaly may contribute to tumor development analogous to what has been suggested for CLTC fusions with ALK in inflammatory myofibroblastic tumors and anaplastic large-cell lymphomas, and with TFE3 in renal cell carcinomas." (PMID 21152103, 2010). "A recent trial reported that the addition of etoposide to CHOP improved event-free survival in young patients with ALK-positive anaplastic large cell lymphomas (event-free survival at 3 years 91.2% versus 57.1%, P = .012), but the overall survival was not significantly different." (PMID 21188274, 2010). "Approximately 20–60% of anaplastic large-cell lymphomas are ALK–." (PMID 16623775, 2006). "In addition, these data show a trend for both peripheral T-cell lymphoma unspecified and ALK- anaplastic large-cell lymphoma to have distinct genetic differences when compared with ETCL, T-prolymphocytic leukaemia and adult T-cell leukaemia/lymphoma." (PMID 16623775, 2006). "Lastly, the classification of ALK– anaplastic large-cell lymphoma is controversial." (PMID 16623775, 2006). "Primary anaplastic lymphoma kinase (ALK)-positive anaplastic large cell lymphoma (ALCL) of the central nervous system (CNS) is an exceedingly rare T-cell malignancy, with only a few adult cases reported worldwide." (PMID 41959915, 2026). "CD25 expression is often detected in ALK+ anaplastic large cell lymphoma (ALCL), but its significance is unclear." (PMID 40507248, 2025). "The presence of anti-ALK antibodies has been reported in anaplastic large cell lymphoma (ALCL) at different time points, suggesting a possible prognostic role." (PMID 40255897, 2025). "Anaplastic lymphoma kinase-positive anaplastic large cell lymphoma (ALK+ ALCL) is an aggressive mature T-cell non-Hodgkin lymphoma." (PMID 41584605, 2025). "At present, there is no standardized first-line treatment regimen for PTCL except for ALK+ anaplastic large cell lymphoma (ALK+ ALCL)." (PMID 40963853, 2025). "In most cases of anaplastic lymphoma kinase–positive anaplastic large cell lymphoma (ALK + ALCL), long-term survival is achieved using CHOP therapy." (PMID 40059232, 2025). "The reported subtype: anaplastic large cell lymphoma, kinase positive (ALCL, ALK+) is an exceedingly rare entity, with the largest case series comprising only 34 cases." (PMID 40699359, 2025). "Mutations in the ALK gene have been identified in a range of tumors, including NSCLC, anaplastic large cell lymphoma (ALCL), and diffuse large cell lymphoma." (PMID 40346640, 2025). "Here, we investigated the effects of pharmacological or genetic HDAC inhibition on NPM::ALK positive anaplastic large cell lymphoma (ALCL) development to assess the potential use of HDACi for the treatment of this disease." (PMID 40175628, 2025). "Six years later, ALK-negative Anaplastic Large Cell Lymphoma (ALK- ALCL) was included as a provisional entity in the WHO classification." (PMID 40565334, 2025). "The incidence steadily increases with age, and the median age at diagnosis is between 60 and 65 years, with the exception of anaplastic lymphoma kinase (ALK)-positive anaplastic large cell lymphoma (ALCL), which is more common in children." (PMID 40227698, 2025).
anaplastic large cell lymphoma (continued). "ALK rearrangements are most commonly observed in anaplastic large cell lymphoma (ALCL) and inflammatory myofibroblastic tumors (IMTs), occurring in 50–80% and ~ 50% of cases, respectively." (PMID 40576713, 2025). "Anaplastic large cell lymphomas (ALCLs) represent a group of CD30-positive T-cell lymphomas that often contain chromosomal rearrangements in the ALK locus and, similar to PTCLs, may contain TP63 rearrangements which are generally associated with poor patient outcome." (PMID 39791744, 2025). "In another PTCL subtype—anaplastic lymphoma kinase (ALK)-positive anaplastic large cell lymphoma (ALCL)—rearrangement of the ALK gene has also been shown to dysregulate the expression of Hypoxia-Inducible Factor (HIF-α) and subsequently VEGFA." (PMID 41295262, 2025). "Notably, CD30 positivity is frequently observed in (EBV+ NT/NKCL), creating diagnostic challenges to distinguish it from ALK-negative anaplastic large cell lymphoma (ALCL)." (PMID 38921179, 2024). "An ALK+ anaplastic large cell lymphoma (ALCL) is a subtype of T-cell lymphoma that features large lymphoid cells characterized by their unique, horseshoe-shaped nuclei and ample cytoplasm." (PMID 37443818, 2023). "Anaplastic lymphoma kinase (ALK)-positive anaplastic large cell lymphoma (ALCL) is an aggressive T-cell lymphoma characterized by large T-cells with strong CD30 and ALK expression." (PMID 38136278, 2023). "In ALK-positive anaplastic large cell lymphoma (ALK+ALCL), a small subset of cancer stem-like (or RR) cells characterized by high Myc expression have been identified." (PMID 37762644, 2023). "The ALK01 clone is commonly used to detect ALK expression in ALK-positive anaplastic large cell lymphoma (ALK + ALCL)." (PMID 38175372, 2023). "With the exception of anaplastic lymphoma kinase (ALK)-positive anaplastic large cell lymphoma (ALK-positive ALCL), their outcome is still unsatisfactory." (PMID 36653509, 2023). "The leukemic phase of ALK‐positive anaplastic large cell lymphoma (ALCL) is reported to have a poor prognosis." (PMID 36794043, 2023). "ALK-positive anaplastic large cell lymphoma (ALCL) represents approximately 6–7% of the mature T-cell lymphomas." (PMID 37655119, 2023). "Crizotinib is the first ALK inhibitor reported as salvage therapy for refractory anaplastic lymphoma kinase‐positive anaplastic large cell lymphoma (ALK+ALCL)." (PMID 36819147, 2023). "ALK (anaplastic lymphoma kinase)-positive anaplastic large cell lymphoma, or ALK+ALCL, is a type of aggressive non-Hodgkin lymphoma of the mature T-cell immunophenotype recognized in the World Health Organization Classification Scheme." (PMID 37762644, 2023). "Later, anaplastic lymphoma kinase-positive anaplastic large cell lymphoma (ALK+ALCL) was recognized as a distinct entity in the 2008 World Health Organization (WHO) classification of malignant lymphomas." (PMID 35406421, 2022). "Minimal disseminated and residual disease (MDD/MRD) analyzed by qualitative PCR for NPM-ALK fusion transcripts are validated prognostic factors in pediatric ALK-positive anaplastic large cell lymphoma (ALCL)." (PMID 35406475, 2022). "Anaplastic lymphoma kinase-positive anaplastic large cell lymphoma (ALK-positive ALCL) is an aggressive form of peripheral T cell lymphoma (PTCL), harbouring an underlying pathogenic ALK fusion gene that produces a constitutively activated tyrosine kinase." (PMID 35154838, 2022). "Studies have shown that PTPN1 and PTPN2 deficiency in anaplastic large cell lymphoma (ALCL) leads to ALK-TKI resistance in ALCL." (PMID 36115852, 2022). "ALK positive anaplastic large cell lymphoma (ALK+ ALCL) has been separated from ALK-negative ALCL (ALK- ALCL) since WHO-HAEM4 based on its distinct pathogenesis and clinical course." (PMID 35732829, 2022).
anaplastic large cell lymphoma (continued). "Twenty-four cases of T-cell lymphoma were identified: twenty-one cases of extranodal NK/T cell lymphoma, nasal type (ENKTCL); two cases of peripheral T-cell lymphoma (PTCL); and one case of anaplastic large cell lymphoma (ALCL) with positive ALK." (PMID 35242496, 2022). "Anaplastic lymphoma kinase-positive (ALK+) anaplastic large cell lymphoma (ALCL) is a distinct T-cell lymphoma type characterized by overexpression and activation of ALK due to chromosomal translocations of ALK gene locus at 2p23." (PMID 35740600, 2022). "Anaplastic large cell lymphomas (ALCL) are mature T-cell neoplasms, approximately half of which harbor rearrangements of the ALK gene that confer a good prognosis." (PMID 34791573, 2022). "Anaplastic lymphoma kinase-positive anaplastic large cell lymphoma (ALK+ALCL) is a kind of peripheral T cell lymphoma (PTCL) presenting large lymphoid cells with ample cytoplasm as well as pleomorphic nuclei." (PMID 35406421, 2022). "ALK+ anaplastic large cell lymphoma (ALK+ ALCL) is a distinct type of aggressive non-Hodgkin lymphoma of T-cell origin, which is characterized by overexpression and activation of ALK kinase due to chromosomal translocations of the gene." (PMID 35740600, 2022). "We recently reported that miR-146a is differentially expressed in ALK+ and ALK− anaplastic large cell lymphoma (ALCL)." (PMID 35676454, 2022). "CD30 and EMA may be positive, and T-cell markers may be aberrantly expressed, causing a potential diagnostic pitfall with ALK-negative anaplastic large cell lymphoma (ALCL)." (PMID 35621636, 2022). "Furthermore, unlike other T cell lymphomas, ALK-negative anaplastic large cell lymphoma does not show a close relationship with infection caused by the Epstein–Barr virus (EBV)." (PMID 35406421, 2022). "The term ALK was coined from a chromosomal rearrangement inside anaplastic large cell lymphoma (ALCL) that was described as a front companion but discovered in 1994." (PMID 35956900, 2022). "PTCL, of which the primary subtypes include anaplastic large cell lymphoma (ALCL) (25%), angioimmunoblastic T-cell lymphoma (33%), and PTCL-NOS (40%), are aggressive lymphomas with poor long-term survival of 35% at 5 years outside of ALK+ ALCL." (PMID 35574379, 2022). "The most common PTCL in children is anaplastic large cell lymphoma (ALCL), and more than 90% of cases have aberrant expression of ALK fusion proteins." (PMID 35955734, 2022). "Other common subtypes of PTCL include PTCL, non-specific (PTCL-NOS), angioimmunoblastic T-cell lymphoma (AITL), and anaplastic lymphoma kinase (ALK)+/− anaplastic large cell lymphoma (ALCL)." (PMID 35559250, 2022). "ALK-positive (ALK+) anaplastic large cell lymphoma (ALCL) is the most common subtype of T-NHL in children and represents about 30% of all pediatric lymphomas." (PMID 35326719, 2022). "Except for anaplastic lymphoma kinase (ALK)–positive anaplastic large cell lymphoma (ALCL), complete and durable response rates are disappointingly low with most commonly employed anthracycline-based regimens." (PMID 35185926, 2022). "Microarray gene-expression profiling, high throughput RT-qPCR, and RNA sequencing of 48 ALK-positive anaplastic large cell lymphoma (ALK+ ALCL) samples obtained at diagnosis enable the identification of genes associated with clinical outcome." (PMID 34771686, 2021). "In the present paper, we characterized on-target effects of crizotinib by specifically evaluating its effects on ALK-positive anaplastic large cell lymphoma (ALK+ ALCL) (which depends on ALK as a major oncogenic and trophic factor)." (PMID 34272360, 2021). "Three patients with lymphoma were also enrolled, including one with T-lymphoblastic lymphoma in PR, one with refractory Sezary syndrome and 1 with ALK+ anaplastic large cell lymphoma (ALCL) in CR3." (PMID 33816524, 2021). "Oncogenic ALK was initially described as a nucleophosmin (NPM)‐ALK fusion in anaplastic large cell lymphoma (ALCL)." (PMID 33411331, 2021).